TIGIT (T cell immunoreceptor with Ig and ITIM domains)
Diseases named in the same sentence as TIGIT in open-access papers (continued):
Sharing a sentence is not in itself a finding about the gene and the disease.
tumor (continued). "In CRC with microsatellite instability (dMMR), an increased frequency of TIGIT overexpression in tumor tissues has been shown among patients with advanced disease, and TIGIT expression is associated with a decrease in median disease-free survival." (PMID 36140182, 2022). "TIGIT is significantly upregulated on chronically stimulated tumor-infiltrating NK and T cells, representing a hallmark of exhausted cytotoxic immune cells." (PMID 36552960, 2022). "LAG3 and TIGIT, two classical ICPs, were detected in tumor-infiltrating lymphocytes and showed a prominent association with other ICPs." (PMID 36246963, 2022). "Several cancers use TIGIT to impair NK and T cell responses either directly, or indirectly through the use of the tumor-associated bacterium Fusobacterium nucleatum." (PMID 35513379, 2022). "Another study revealed that TIGIT causes polarisation of CD155-expressing type 1 proinflammatory macrophages into IL-10-secreting type 2 macrophages (which are tumour-promoting) in mice." (PMID 35328510, 2022). "In other words, by interacting with three ligands (CD155, CD112, and CD113) expressed on the surface of tumor cells, TIGIT causes the immune system to be suppressed." (PMID 36276117, 2022). "In patients, high TIGIT/DNAM-1 ratio on tumor-infiltrating Tregs has been found to be associated with poor clinical outcomes in melanoma following anti-PD-1 or anti-CTLA-4 therapies." (PMID 35273608, 2022). "We discovered that the presence of metastatic tumor cells was associated with higher fraction of T cells expressing the exhaustion markers PD‐1 and TIGIT." (PMID 34165864, 2022). "TIGIT thus appears to mark hypofunctional TILs in MPM, caused both by the presence of TIGIT-positive Tregs, as well as TIGIT expression on tumor-infiltrating CD8+ T cells." (PMID 35327475, 2022). "Our results confirm the observation of TIGIT to be positively associated with patient survival, which is completely novel for the tumor entity OSCC." (PMID 36551992, 2022). "TIGIT expression is upregulated in the tumor microenvironment in multiple malignancies and its expression on tumor infiltrating lymphocytes (TILs) has been associated with poor survival." (PMID 35273608, 2022). "In the context of cancer, TIGIT deficiency, or prophylactic antibody blockade, yields a modest level of protection against primary tumor growth in mice." (PMID 35812451, 2022). "Another novel drug class with potential activity on NK is represented by the inhibitors of TIGIT; indeed, TIGIT blockade is associated with prevention of NK exhaustion and enhancement of NK anti-tumor immunity." (PMID 36291830, 2022). "Similar to previous reports, tumor-associated macrophages suppress tumor T cell infiltration and TIGIT-NECTIN2 interaction regulates the immunosuppressive environment in HBV-associated HCC." (PMID 35619708, 2022). "The authors observed both activated and exhausted tumor-infiltrating NK cells and TILs and TIGIT upregulation in the TME, especially on NK cells, associated with superior distant disease recurrence-free and OS." (PMID 35656508, 2022). "The observed anti-tumor efficacy is associated with a pharmacodynamic change of TIGIT down-regulation and Treg reduction." (PMID 35273608, 2022). "Suppression of tumour growth was associated with a reduced expression of immune checkpoint molecules, PD-1, TIGIT and LAG-3 with upregulation of CXCR3 expression." (PMID 36104795, 2022). "The interaction of TIGIT with other constituents of the tumor microenvironments (TMEs), such as cancer-associated fibroblasts and angiogenesis, remains to be elucidated." (PMID 34025438, 2021). "TIGIT is a cell receptor that regulates T-cell-mediated tumour recognition, and as such fits the theorised POLE-mutated phenotype." (PMID 34830795, 2021). "Tumor-infiltrating NK cells expressed high levels of TIGIT, and TIGIT+ NK cells displayed impaired activity associated with increased expression of the inhibitory receptors TIM-3 and LAG-3 in comparison with TIGIT− NK cells." (PMID 34885076, 2021).
tumor (continued). "We show the cellular and immunosuppressive landscapes that suggest functions of tumor-associated macrophages and TIGIT–NECTIN2 interaction in shaping a cancer-promoting immunosuppressive environment in hepatocarcinogenesis." (PMID 34140495, 2021). "We also uncovered that the high-risk cluster exhibited elevated expression levels of PD1, PDL1, CTLA4, LAG3, and TIGIT compared to the low-risk counterpart, supporting the contribution of hypoxia to the tumor immune escape in HCC." (PMID 34917132, 2021). "In preclinical mouse tumor models, TIGIT deficiency delays the subcutaneous growth of both B16F10 and MC38 cells and lung metastasis of B16 cells." (PMID 33670993, 2021). "Here the authors use single cell RNA sequencing to identify TIGIT-NECTIN2 as a pathway by which tumour-associated macrophages reduce intratumour T cell activation." (PMID 34140495, 2021). "We found that tumor-associated macrophages suppress tumor T cell infiltration and TIGIT-NECTIN2 interaction regulates the immunosuppressive environment." (PMID 34140495, 2021). "TIGIT expression on tumor-infiltrating NK cells is associated with tumor progression and is linked to functional exhaustion of NK cells in multiple cancer models." (PMID 34367161, 2021). "In one study, anti-PD-1 on PD-1+Tim-3+ tumor-specific CD8+ T cells was associated with the up-regulation of TIGIT in melanoma." (PMID 34507594, 2021). "The presence of CD30, OX40, and 4-1BB, and the upregulation of TIGIT were in line with the memory phenotype of tumor-infiltrating Tregs, given the association of these molecules with activated T cells." (PMID 33527196, 2021). "The current study has shown that the elevated expression of TIGIT in the tumor microenvironment is associated with inferior OS." (PMID 34638729, 2021). "NK-cell specific deficiency of TIGIT prevented tumor metastasis and improved survival in a mouse model of melanoma." (PMID 33766099, 2021). "CD4+LAIR2+ cells highly expressed Treg cell lineage markers, including IL2RA, CTLA4, TNFRSF18, ICOS, TIGIT, and tumor-associated Treg cell marker CCR8, consistent with CD4+ LAIR2+ cells being of Treg lineage and not recently activated T cells." (PMID 35008369, 2021). "In particular, TIGIT is an immunoreceptor inhibitor checkpoint that has been implicated in tumor immunosurveillance." (PMID 35069212, 2021). "It is now recognised that TIGIT expression on tumour-infiltrating NK cells is associated with tumour progression and was also linked to functional immune exhaustion." (PMID 33995362, 2021). "TIGIT is the most well understood and blocking TIGIT gives rise to a potent NK anti-tumor effect, which is attributed to both loss of NK inhibition and enhanced activation." (PMID 32290478, 2020). "Together, these results suggest that CD155 and TIGIT are associated with tumor progression and tumor metastasis in PSCCE." (PMID 33490104, 2020). "It has been recently demonstrated that TIGIT is highly expressed on tumor-infiltrating NK cells and associated with NK cell exhaustion in different tumor models and patients with colon cancer." (PMID 31867006, 2019). "TIGIT blockade improved prognosis in murine T and B-deficient, NK-sufficient xenograft models against several human tumor cell lines including colon, breast, melanoma, and fibrosarcoma." (PMID 31456796, 2019). "TIGIT expression has been reported as upregulated in tumor-associated NK cells in different malignancies." (PMID 31214193, 2019). "Higher TIGIT expression was observed in the tumor region of HCC patients and was potentially linked to tumor progression." (PMID 31507621, 2019). "It has been shown that, in patients with colon cancer, TIGIT expression is increased on tumor associated NK cells." (PMID 31105707, 2019). "Frequent co-expression with exhaustion markers such as PD-1 is an extra argument to develop anti-TIGIT blocking antibodies as a therapeutic approach to reverse T or NK cell dysfunction associated with tumor immune escape." (PMID 30400822, 2018).
tumor (continued). "The binding of Fap2 to TIGIT was found to inhibit the activity of natural killer (NK) cells against the tumor cells, thus causing the growth and progression of CRC." (PMID 29619076, 2018). "Pre-clinical tumor studies showed that the specific co-inhibition of the TIGIT and PD-1 checkpoint axis causes a significant enhancement of anti-melanoma immune responses by increasing the effector function of cytotoxic T cells." (PMID 28073373, 2017). "A gene signature-based approach identified TIGIT expression as a marker for tumor-associated T cells." (PMID 26347741, 2015). "Integration of our own cytokine correlation analysis and GSEA results suggests that the TIGIT/CD155 immune checkpoint axis may be associated with multiple immune-related pathways in CRC tumor tissues." (PMID 41596586, 2026). "Immunogenomic analyses linked high DCAF7 to CD4+ T‐cell enrichment, broad upregulation of checkpoint genes (PD‐1/PD‐L1, CTLA‐4, TIGIT), and increased tumour mutational burden, microsatellite instability and neoantigen load, suggesting an immune‐evasive phenotype." (PMID 41472554, 2026). "Loss of TIGIT results in increased susceptibility to autoimmunity, while promoting tumor clearance." (PMID 41094201, 2025). "In addition, high TIGIT expression is associated with the exhaustion of tumor-infiltrating NK cells." (PMID 39847233, 2025). "Some investigators have suggested that TIGIT overexpression could be closely associated with T-cell exhaustion, occurring in advanced tumor stages and following cancer cell antigen exposure." (PMID 40890162, 2025). "TIGIT expression’s association with tumor advancement underscores its significance." (PMID 39939322, 2025). "ATC accentuates this pattern: LAG-3, HAVCR2 and TIGIT co-expression defines a terminally dysfunctional CD8/γδ T-cell pool whose clonal diversity contracts in parallel with rising tumour mutational burden, suggesting neo-antigenic pressure but failed immune pruning." (PMID 40959084, 2025). "Additionally, in a number of malignancies, the expression of TIGIT was associated with tumor stage, survival, and the TILs component." (PMID 38229100, 2024). "Higher pre-treatment tumor PD-L1 and TIGIT RNA expression are associated with complete response." (PMID 38789460, 2024). "Higher pre-treatment tumor PD-L1 and TIGIT RNA expression were associated with complete response." (PMID 38789460, 2024). "Moreover, these ligands are predominantly expressed by tumor cells, tumor-infiltrating myeloid cells, and antigen-presenting cells (APCs), underlining TIGIT’s role in TME-specific T cell immunosuppression." (PMID 39409893, 2024). "Consistent with our previous experiments, scRNA-seq analysis of tumour CD8+ T cells showed that treatment with anti-PD-L1 + anti-TIGIT antibodies drove reduced expression of genes associated with exhaustion and increased expression of a memory-like gene program relative to single-agent treatment." (PMID 38418879, 2024). "We first investigated the efficacy of anti-TIGIT Fc variants in controlling tumour growth." (PMID 38418879, 2024). "Several checkpoint and inhibitory receptors, such as PD-1 (gene name: PDCD1), CTLA4, TIM-3 (HAVCR2), LAG3, CD39 (ENTPD1), CD160, KLRG1, CD96, BTLA, 2B4, and TIGIT, have been implicated in the reduction of immune activity and response in the tumor micro-environment." (PMID 39513882, 2024). "Additionally, an increased TIGIT to CD226 ratio in the tumour microenvironment has been associated with a higher frequency of activated Tregs, as well as an unfavourable prognosis." (PMID 38443832, 2024). "In addition, TIGIT expression was associated with a higher tumor grading, indicating a prognostic relevance of M2 infiltration in HGSOC." (PMID 37876933, 2023). "In addition, the expression of Siglec10 and SIRPα had strong associations with macrophages while TIGIT had weak associations with macrophage among almost all tumor types." (PMID 38016957, 2023).
tumor (continued). "Furthermore, the high levels of PD-1, PD-L1, CTLA-4, LAG-3, SIGLEC15, and TIGIT were associated with poor prognosis and immunosuppression of the tumor microenvironment in ccRCC." (PMID 37175461, 2023). "In addition, TIGIT was associated with adenosine receptor signaling in T cells and the kynurenine pathway in tumor cells, both altering the tumor microenvironment and T cell-mediated immunity against tumors." (PMID 36874131, 2023). "For instance, oncolytic VACVs encoding a single chain variable fragment against TIGIT induced effective anti-tumor immunity and achieved a profound remodeling of the inhibitory tumor microenvironment from a “cold” state to a “hot” state synergizing with PD-1 or LAG-3 blockade." (PMID 38283361, 2023). "Seven ICIs, excluded LAG3 and TIGIT were detected to have higher expression levels in the high-risk group, which may be related to the higher tumor grade of patients in which group." (PMID 37355624, 2023). "Thus, tumor exposure resulted in close to 80% loss in the IFNγ generation capacity with about 30% of this loss being dependent on TIGIT/PVR engagement." (PMID 37345049, 2023). "Moreover, in the tumor-bearing murine models, TIGIT blockade or deficiency resulted in more DNAM-1+ cells (~15% more)." (PMID 37345049, 2023). "High expression of CD155 and TIGIT has been associated with adverse prognosis in many tumours." (PMID 37803304, 2023). "Indeed, even in CD226-deficient mice, TIGIT blockade was still able to dramatically reduce tumour burden in a murine cancer model, although mice were in general less able to control tumours." (PMID 37596248, 2023). "Therefore, the deficiency of TIGIT alleviates NK-cell exhaustion and slows tumor growth, which elicits potent antitumor immunity." (PMID 35669786, 2022). "TIGIT, as the only downregulated immune checkpoint in the high-risk group, is primarily expressed on T cells and NK cells, which can inhibit anti-tumor immunity by impairing T cell functions, preventing NK cell-mediated lysis, and enhancing the suppressive activity of regulatory T cells." (PMID 35974300, 2022). "Consequently, TIGIT was found to be highly expressed on tumor-infiltrating lymphocytes (TILs), and high levels of TIGIT expression have been associated with tumor progression." (PMID 35327475, 2022). "Although multiple sources of evidence support the critical role of TIGIT in limiting tumor-specific adaptation and innate immunity, the role of TIGIT and its association with the tumor-immune microenvironment in BC remains largely unknown." (PMID 35154317, 2022). "The results strongly indicated that TIGIT was well associated with tumor immunity." (PMID 36211383, 2022). "Besides, the overexpression of TIGIT in infiltrating lymphocytes exhibited functional failure and hyporesponsive state, which was associated with the advanced stage of tumor." (PMID 35433470, 2022). "High expression of TIGIT is associated with the exhaustion of tumor-infiltrating NK cells." (PMID 35669786, 2022). "Moreover, TIGIT deficiency in NK cells alone was sufficient to delay tumor growth independently of the adaptive immune system." (PMID 35008385, 2022). "Therefore, the blockade of checkpoint receptor TIGIT, associated with the exhaustion of tumor-infiltrating NK cells, has been shown as a promising strategy in the preclinical treatment of colon cancer." (PMID 36612114, 2022). "Higher TIGIT expression was also associated with higher T stage and nodal invasion but not with other clinicopathological variables such as age, gender, smoke/alcohol use, tumor site, and tumor differentiation." (PMID 35656508, 2022). "S2 was characterized as a ‘cold tumor’ profile with the highest tumor purity score, and S3 as an ‘immunosuppressed tumor’ profile with the poorest prognosis and a high expression level of immunosuppressive genes such as cytotoxic T‐lymphocyte‐associated protein‐4, TIGIT, and PDCD1." (PMID 35124891, 2022).
tumor (continued). "Indeed, tumor-infiltration by CD8+ T cells with poor CD226 expression and high levels of the other specific ligand of CD155 (T cell immunoreceptor with Ig and ITIM domains, TIGIT), is associated with T cell exhaustion and tumor progression." (PMID 36428727, 2022). "Based on the mechanism underlying TIGIT-mediated regulation of anti-tumor immune responses, efforts have been made to enhance T or NK cell activity by blocking TIGIT binding to its ligands, PVR and nectin-2, with monoclonal antibodies (mAbs) for therapeutic interventions." (PMID 33670993, 2021). "Notably, tumour CD155 (the binding partner for TIGIT) expression has been linked with resistance to αPD-1 therapy in patients with metastatic melanoma, while expression of CD155 on cancer cells ablates CTL activation via CD226 degradation." (PMID 33401460, 2021). "Besides, the increased infiltration of tumor-infiltrating TIGIT+CD8+ is associated with the worsened OS and RFS of affected patients." (PMID 34638729, 2021). "Some important immune-associated genes, such as granzyme B, IFN-γ, IL-2, IL-12, FoxP3 and STING, are regulated via epigenetic mechanisms in immune or/and cancer cells, as are immune checkpoint molecules (PD-1, CTLA-4, TIM-3, LAG-3, TIGIT) expressed by immune cells and tumor-associated stromal cells." (PMID 34930302, 2021). "Moreover, TIGIT expression on tumor-infiltrating NK cells is associated with tumor progression in tumor-bearing mice and patients with colon cancer and it is linked to the functional exhaustion of NK cells." (PMID 33321719, 2020). "Importantly, we expect the pro-tumorigenic effect of F. nucleatum to be much stronger in humans because the activity of the NK and few T cells present in the tumor will be further weakened by inhibitory interactions of Fap2 with TIGIT and of CbpF with CEACAM1." (PMID 32591509, 2020). "In the tumor microenvironment, the highly expressed TIGIT in TILs may cause local immune tolerance and promote cancer metastasis and progression by modulating the activation of NK cells, DCs, and T cells." (PMID 32849489, 2020). "Future work investigating the effect of VISTA and PD-1 combination blockade on other co-inhibitory receptors (TIM-3, LAG-3, TIGIT) and inhibitory cell types (regulatory T cells, tumor associated macrophages) will be necessary to more comprehensively define the therapy’s mechanism of action." (PMID 32938950, 2020). "Recent evidence showed the upregulation of TIGIT on tumor-infiltrating NK cells in mouse models of subcutaneously administered solid tumors and the TIGIT expression on tumor-infiltrating NK cells was associated with tumor progression and was linked to functional exhaustion of NK cells." (PMID 30805309, 2019). "TIGIT expression on Tregs has been associated with a highly immune-suppressive phenotype in tumor tissue and TIGIT signaling in Tregs may favor Treg stability." (PMID 30863404, 2019). "Taken together, the combination of an anti-TIGIT and anti-PD-1 therapy could be a promising approach with associated stratified tumor entities in the future." (PMID 28073373, 2017). "Further, the expressions of PD-1, TIM-3 and TIGIT were upregulated in tumor infiltrating lymphocytes (TILs), which might be associated with TILs exhaustion." (PMID 27577071, 2016). "Furthermore, TIGIT on T cells inhibits T-cell responses that are implicated in anti-tumor and anti-viral immunity." (PMID 26735971, 2016). "Since TIGIT has been implicated in enhancing the suppressive function and stability of regulatory T cells, particularly in inflammatory and tumor settings, this reduction may indicate a shift toward a less suppressive or destabilized peripheral Treg phenotype in NSCLC patients with brain metastases." (PMID 40346687, 2025). "Furthermore, several studies have provided increasing evidence that high TIGIT expression is observed on tumor infiltrating NK cells and is associated with their functional exhaustion, and that TIGIT blocking can boost anti-tumor immunity." (PMID 36845105, 2023).